TLR4 (toll like receptor 4)
Diseases named in the same sentence as TLR4 in open-access papers (continued):
Sharing a sentence is not in itself a finding about the gene and the disease.
atherosclerosis (continued). "Dysregulated Toll-like receptor (TLR)-4 activation is involved in acute systemic sepsis, chronic inflammatory diseases, such as atherosclerosis and diabetes, and in viral infections, such as influenza infection." (PMID 28106157, 2017). "In this study, we investigated the effects of TLR4 antagonist TAK-242 on development of graft atherosclerosis in a model of aorta transplantation." (PMID 29150694, 2017). "Our work has focused on defining the role of TLR2 and TLR4 signaling in P. gingivalis-mediated inflammatory atherosclerosis using a well-defined hyperlipidemic mouse model (ApoE−/−)." (PMID 28348558, 2017). "Our results suggest an essential role of DC-SIGN/TLR4 signaling in macrophages in the pathogenesis of atherosclerosis." (PMID 28607410, 2017). "It has been postulated that the association between microbial infection and atherosclerosis involves common mechanisms of signaling via TLR2 and TLR4." (PMID 28348558, 2017). "Different from endolysosomal TLRs, cell surface TLRs such as TLR2 and TLR4 have been proven detrimental in atherosclerosis from most tested experimental models." (PMID 28405010, 2017). "Minimally modified LDL (a subtype of oxLDL that is essential for atherosclerosis) induces ROS production and macrophage cytoskeletal rearrangements in a TLR4 dependent and MyD88-independent manner." (PMID 27795867, 2016). "Further investigations using ApoE null mice with either constitutive expression or knockout of the fibronectin EDA domain showed that EDA+FN promotes progression of atherosclerosis through a mechanism that is partially dependent on TLR4." (PMID 27795867, 2016). "Toll-like receptor 4, which is broadly expressed on the plasma membranes of immune cells, plays a vital role in initiating the sterile inflammation related to atherosclerosis." (PMID 27777559, 2016). "The detrimental role of TLR4 in atherosclerosis through monocytes and macrophages is well established." (PMID 27095356, 2016). "For instance, TLR2 and TLR4 participate in the pathogenesis of atherosclerosis, autoimmune colitis, systemic lupus erythematosus (SLE), diabetes and Alzheimer’s disease." (PMID 26987407, 2016). "As expected, the lesions in CUMS + siRNA group, and CUMS + PDTC group were significantly reduced compared with CUMS group, respectively (both P < 0.05), indicating that inhibition of TLR4/NF-κB obviously attenuated CUMS-induced atherosclerosis." (PMID 25860573, 2015). "In summary, our studies demonstrate that TLR4/NF-κB pathway is involved in CUMS-induced the development of atherosclerosis." (PMID 25860573, 2015). "In another study, double knockout mice for ApoE and TLR4 (ApoE−/−/TLR4−/−) also showed markedly reduced atherosclerosis and altered plaque phenotype, despite persistent hypercholesterolemia." (PMID 25757594, 2015). "To address the pathophysiological roles of TLR4/NF-κB signaling in the development of atherosclerosis induced by CUMS, we evaluated the influence of TLR4 knockdown and NF-κB inhibition on the atherosclerosis in apoE-/- mice." (PMID 25860573, 2015). "Together these experimental data confirm the major role of TLR4/NFκB pathway in the crosstalk between inflammation, atherosclerosis, and metabolism dysfunctions." (PMID 25873766, 2015). "Our results indicated that CUMS apoE-/- mice treatment with siRNA TLR4 significantly decreased atherosclerosis and down-regulated TLR4, NF-κB, and inflammatory cytokines." (PMID 25860573, 2015). "Our previous study indicated that CUMS dramatically accelerated atherosclerosis and elevated TLR4 and NF-κB in apoE-/- mice." (PMID 25860573, 2015). "Apolipoprotein E deficiency (ApoE−/−) combined with a high-fat Western-type diet (WD) is known to activate the toll-like receptor (TLR4) pathway and promote atherosclerosis." (PMID 25975841, 2015). "Increasing evidence points to a significant role of Toll-like receptor 4 (TLR4), a key player in innate immunity, in the pathogenesis of atherosclerosis." (PMID 25757594, 2015).
atherosclerosis (continued). "In this study, we have investigated the role of TLR4/NF-κB pathway in CUMS-induced atherosclerosis in apoE-/- mice." (PMID 25860573, 2015). "Among the various signal transduction pathways implicated in proatherogenic inflammation, the Toll-like receptor 4 (TLR4)/nuclear factor kappa B (NF-κB) pathway has recently aroused more attention due to its important roles in atherosclerosis." (PMID 25860573, 2015). "Our previous studies have shown that chronic unpredictable mild stress (CUMS) accelerates atherosclerosis and up-regulates TLR4/NF-κB expression in apoE-/- mice." (PMID 25860573, 2015). "Taken together, these data support the important role of 27-OH and HNE in atherosclerosis instability, and for the first time, we have demonstrated that these oxidized lipids act as endogenous ligands of TLR4." (PMID 25757594, 2015). "We expected to illuminate the roles of TLR4/NF-κB pathway in chronic stress-induced atherosclerosis." (PMID 25860573, 2015). "TLR4 activation by its ligands elicits signal transduction to induce the inflammatory response, which results in initiation and progression of atherosclerosis." (PMID 25860573, 2015). "Further studies are needed to explore which TLR4 is a critical to inhibit atherosclerosis-induced by CUMS." (PMID 25860573, 2015). "To further reveal the mechanisms of reducing atherosclerosis lesions by blocking TLR4/NF-κB, we investigated the effects of Ad-TLR4 siRNA and NF-κB antagonist PDTC on inflammatory cytokines such IL-1β, MCP-1, and TNF-α." (PMID 25860573, 2015). "Atherosclerosis development in murine models has largely been shown to be associated with increased expression of TLR-2 and TLR-4." (PMID 26101539, 2015). "The current notion that Toll-like receptor 4 (TLR4) plays pivotal functions during atherosclerosis has garnered increased interest." (PMID 26492242, 2015). "TLR4 is widely expressed on different cell types in vessel wall known to be involved in the pathogenesis of atherosclerosis." (PMID 25860573, 2015). "Among these members, TLR4 has drawn more attention during the development progress of atherosclerosis." (PMID 24502419, 2014). "As a key component of innate immune response, TLR4 possesses a pivotal role in the initiation and progression of atherosclerosis, and can regulate the inflammatory response in macrophages via its downstream NF-κB signaling." (PMID 24502419, 2014). "The recent reports correlating the microbial infections with chronic disorders such as atherosclerosis have lead to questions in relation to the role of microbial sensors such as TLR4 in an intriguing phenomenon of the inflammation-induced angiogenesis." (PMID 25071774, 2014). "From the point of view of atherosclerosis, a role for TLR4 in the initiation and progression of the disease is widely recognized." (PMID 24847266, 2014). "Further analysis manifested that miR-21 negatively regulated lipid-laden foam cell formation and inflammatory responses in LPS-stimulated macrophages through the TLR4-NF-κB pathway, indicating a critical roles of miR-21 in the progression of atherosclerosis." (PMID 24502419, 2014). "TLR4 is expressed on the cell surface of the main cell types involved in atherosclerosis, endothelial cells, platelets and macrophages." (PMID 24847266, 2014). "Growing evidence indicates that TLR4 plays a very important role in macrophage foam cells formation, indicating a critical roles of TLR4 in atherosclerosis via regulating lipid deposition." (PMID 24502419, 2014). "There is evidence regarding a role for the TLR4 signaling pathway and the innate immune response in the development of cardiovascular pathologies with an inflammatory component such as atherosclerosis, diabetes and pre-eclampsia." (PMID 25093580, 2014). "The binding of LPS monomers to soluble CD14 expressed by endothelial cells induces cytokine production and atherosclerosis through the Toll-like receptor 4 signaling pathway." (PMID 25286027, 2014).
atherosclerosis (continued). "Whole-body knock out mice of TLR2, TLR4 and some of the signaling proteins mentioned here were demonstrated to have reduced atherosclerosis progression." (PMID 25429291, 2014). "Inhibiting the TLR4-mediated signaling pathway can prevent atherosclerosis developing, as has been verified in some in vitro studies." (PMID 24667766, 2014). "Infection of ApoE−/− TLR4−/− mice, fed a high-fat diet, with C. pneumoniae resulted in diminished atherosclerosis compared to ApoE−/− infected mice." (PMID 25010102, 2014). "Considerable and convincing evidence links the pathophysiology of atherosclerosis, cardiac dysfunction, congestive heart failure, and other vascular diseases with the TLR-4-mediated signaling pathway, as amply stressed by Frantz and colleagues." (PMID 25120286, 2014). "I.e.TLR-4 has been shown to be involved in early atherosclerosis by comparing knock out mice to control animals: Mice lacking TLR-4 were protected in an atherosclerosis model, which seemed to be independent from cholesterol levels." (PMID 24498948, 2013). "Studies of atherogenesis in mice support a role for TLR4 in the development of diet-induced atherosclerosis as well." (PMID 24376657, 2013). "The attenuated cytokine response from 11βHSD1-deficient macrophages following TLR4 agonist stimulation with oxidized LDL suggests that 11βHSD1 is important for potentiating TLR4-dependent activation and signaling in the setting of atherosclerosis." (PMID 23383297, 2013). "As a common ligand of TLR4, LPS is considered as crucial for the initiation and development of atherosclerosis." (PMID 23072373, 2012). "As a receptor of LPS, TLR4 and its downstream signaling effectors, NF-κB, are pivotal in the initiation and development of atherosclerosis." (PMID 23072373, 2012). "Based on these results, we can conclude that LPS can induce lipid-laden foam cells formation via MCP-1 production and lipid deposition by TLR4-NF-κB pathway, and accelerate the pathogenesis of atherosclerosis." (PMID 23072373, 2012). "Many factors can serve as a mediator/inducer of atherosclerosis by interaction with a common inflammation pathway-TLR4, including heat shock protein (HSP60) and LPS." (PMID 23072373, 2012). "TLR4 is expressed on a variety of cells, including ECs and VSMCs, and thus initiates and sustains the inflammatory response in atherosclerosis." (PMID 22292067, 2012). "Recent data directly implicate signaling by TLR4 in the pathogenesis of atherosclerosis, establishing a key link between atherosclerosis and defense against both foreign pathogens and endogenously generated inflammatory ligands." (PMID 22104447, 2011). "There has been shown to be co-localisation of p65 (an NFκB family member) with both TLR2 and TLR4 in macrophages in atherosclerosis." (PMID 21526997, 2011). "Toll-like receptor 4 (TLR4) affects the inflammatory response that influences initiation and progression of atherosclerosis." (PMID 20308035, 2010). "Antagonism of TLR-2 or TLR-4 signalling is currently perceived as the most attractive target for development of therapeutics for the treatment of atherosclerosis." (PMID 20652007, 2010). "Chronic inflammation activated by macrophage innate pathogen recognition receptors such as TLR4 can lead to a range of inflammatory diseases, including atherosclerosis, Crohn's disease, arthritis and cancer." (PMID 20205812, 2010). "Whole body disruption of TLR4 signaling prevents atherosclerosis in proatherogenic genetic mouse models." (PMID 20814545, 2010). "In another study, overexpression of TLR2 and TLR4 in the carotid arterial vessel wall in a rabbit model led to accelerated atherosclerosis in animals fed a high fat diet." (PMID 20676278, 2009).
atherosclerosis (continued). "First was the analysis of the TLR4-T399I polymorphism and second was the fact that no individuals with overt coronary artery disease or stroke were enrolled, considering the possible contribution of TLR4 SNPs in atherosclerosis development." (PMID 20169003, 2009). "Evidence is also accumulating for a potential role for TLRs, particularly TLR4, in the development of atherosclerosis." (PMID 20676278, 2009). "This may be due to the increased expression of Toll-like receptor 4 (TLR4) during atherosclerosis, which leads to increased expression of pro-inflammatory factors such as TNF-α and IL-1β and decreased expression of anti-inflammatory factors such as TGF-β." (PMID 41590849, 2025). "At the organ level, DAMP-induced TLR signaling drives pathology across systems: TLR4 activation accelerates atherosclerosis, HMGB1 promotes plaque instability, and microglial TLR4 activation by HMGB1 or S100 proteins fuels neuroinflammation and cognitive decline." (PMID 41373468, 2025). "PCSK9 activates PKCδ, Syk and NF-κB, promoting atherosclerosis progression independently of LDL-R.In apoE-/- mice, the inactivation of PCSK9 has been shown to effectively suppress vascular inflammation and atherosclerosis by reducing the TLR4/NF-κB signaling pathway." (PMID 40354375, 2025). "In addition, PF not only ameliorates atherosclerosis by inhibiting TLR4-mediated NF-κB activation but also inhibits OX-LDL-induced apoptosis and inflammation in human coronary artery endothelial cells by regulating the Wnt/β-catenin pathway." (PMID 40815470, 2025). "Together, these results suggested a pivotal role for TLR4 in atherosclerosis progression." (PMID 38445291, 2024). "Our in vivo data of proteomics and immunostaining showed that, compared with WT group, MerTK-/- aggravates atherosclerosis in d-flow areas through upregulation of endothelial dysfunction markers (e.g. IL-1β, NF-κB, TLR4, MAPK signaling, vWF, VCAM-1 and p22phox) and mitochondrial dysfunction." (PMID 38646649, 2024). "We consider this an appropriate model to complement our in vivo atherosclerosis studies since (i) TLR4 and its' signalling pathways play a major role in atherosclerosis progression and (ii) atherosclerosis-relevant stimuli like oxLDL do not induce itaconate in vitro (data not shown)." (PMID 38309122, 2024). "LPCAT3 regulates the expression of C-SRC and TLR4, and promotes the development of atherosclerosis." (PMID 38519981, 2024). "have revealed that olfactory receptor 2 (Olfr2) interacts with TLR4 in vascular macrophages leading to NLRP3 inflammasomes activation via adenylate cyclase 3 (Adcy3) to drive atherosclerosis development, provides a new target for the prevention and treatment of atherosclerosis." (PMID 38803504, 2024). "This study preliminarily indicated that miR-218-5p in macrophage-derived foam cells may affect cell function and inflammatory response through up-regulation of TLR4 expression, and then participate in the development of atherosclerosis." (PMID 36890438, 2023). "Moreover, miRNA-146a-5p binds to the 3’untranslated region of the TRAF6 gene and inhibit its expression,ultimately reducing vascular TRAF and TLR4 signaling and vascular inflammatoryresponse in atherosclerosis." (PMID 39076378, 2023). "TLR4 has been demonstrated to play a role in both the early and late stages of atherosclerosis." (PMID 37830572, 2023). "An increase in the number of circulating TLR4-positive intermediate monocytes (>447.0–467.0 cells/μL) was an independent predictor of the short-term progression of lower limb artery atherosclerosis (p < 0.0001) and polyvascular atherosclerosis (p = 0.003)." (PMID 37569579, 2023). "The beneficial effect of inhibiting TLR4 on endothelium-dependent vasodilation has been described by our group and others in several models of hypertension and atherosclerosis." (PMID 36937865, 2023).
atherosclerosis (continued). "We analyzed the relationships of TGFβ and TLR4-positive intermediate monocytes (as indicators that showed independent prognostic value in relation to the progression of atherosclerosis) as well as T-regulatory lymphocytes, with other immunity-related markers and indicators of plaque burden." (PMID 37569579, 2023). "Calprotectin binds to Toll-like receptor 4 (TLR4), which mediates inflammation and atherosclerosis." (PMID 36984554, 2023). "While in TLR-2 and LDL-R-deficient mice, angiotensin II infusion resulted in AAA formation but not atherosclerosis, both were attenuated in mice deficient in TLR-4 and LDL-R." (PMID 37508529, 2023). "Toll-like receptor 4 (TLR4), an integral membrane receptor, has been closely associated with the pathogenesis of atherosclerosis and exhibits elevated expression levels in atherosclerotic lesions at different stages of atherogenesis in both humans and murine models." (PMID 37520489, 2023). "Interestingly, and in line with the current study, previous reports have suggested that TLR4−/− mice are partially protected from vascular inflammation and atherosclerosis following a HFD." (PMID 39323483, 2023). "The expression of miR-218-5p is reduced in atherosclerosis, and it may regulate the inflammatory response of atherosclerotic foam cells by targeting TLR4, suggesting that miR-218-5p may be a promising target for clinical atherosclerosis therapy." (PMID 36890438, 2023). "miR-146a/b-5p can regulate TLR4 downstream moleculesinterleukin-1 receptor-associated kinase 1 (IRAK1) and tumor necrosis factorreceptor-associated factor 6 (TRAF6), thereby resisting atherosclerosis." (PMID 39076378, 2023). "The increased PCSK9 could accelerate atherosclerosis through activating the TLR4/NF-κB signaling pathway and promoting inflammation." (PMID 36970356, 2023). "Moreover, flavonoids exhibited anti-atherosclerosis properties through anti-inflammatory mechanisms like the TLR4/NF-κB pathway and the AMPK-SIRT1 signaling." (PMID 38026172, 2023). "Moreover, TLR4 was upregulated in macrophages under HG and monocytes of subjects with diabetes and atherosclerosis." (PMID 37237950, 2023). "We found that reduced levels of macrophage plasma membrane sphingolipids could effectively prevent inflammatory responses by reducing TLR4 expression 45-47, thereby reducing atherosclerosis 45,46,48." (PMID 35711841, 2022). "By utilizing VSMCs-lineage tracing technology and single-cell RNA sequencing (scRNA-seq), we demonstrate that the ETs from CD68+ VSMCs influence the progress of atherosclerosis by regulating the direction of VSMCs’ transdifferentiation through STING-SOCS1 or TLR4 signaling pathway." (PMID 36473863, 2022). "Third, there are many potential receptors for SAA1, and our study clarified only the potential role of TLR4 signaling in SAA1-induced atherosclerosis; whether other receptors also play corresponding functions needs to be further explored." (PMID 36158875, 2022). "Deficiency of serine palmitoyltransferase subunit 2, a key enzyme involved in the ceramide de novo synthesis pathway, could reduce murine atherosclerosis partly by attenuating TLR4 recruitment and downstream NF-κB-mediated inflammation." (PMID 35211530, 2022). "In conclusion, our findings suggest that Pg-LPS may promote atherosclerosis via the activation of MAPK through TLR4." (PMID 36613563, 2022). "Based on these, we propose the hypothesis that QB can reduce the inflammatory response and delay disease progression in SLE combined with atherosclerosis by inhibiting the HMGB1/TLR4/MyD88 pathway." (PMID 35571092, 2022). "Additionally, TLR4 has been demonstrated to be related to various pathological progression, including autoimmune diseases, neurodegenerative diseases, atherosclerosis, and cancer." (PMID 35401188, 2022).